MMP2 (matrix metallopeptidase 2)
Diseases named in the same sentence as MMP2 in open-access papers (continued):
Sharing a sentence is not in itself a finding about the gene and the disease.
Crohn disease (10 papers, 2011 to 2024). A gastrointestinal disorder characterized by chronic inflammation involving all layers of the intestinal wall, noncaseating granulomas affecting the intestinal wall and regional lymph nodes, and transmural fibrosis. "On the other hand, MMP-2 and its increased expression were observed in perianal fistulas in Crohn’s disease." (PMID 38338780, 2024). "A study assessing the expression pattern of MMPs in fistulas of patients with Crohn’s disease also demonstrated elevated expression of MMP-9 (using immunohistochemical method) with MMP-2 remaining at similar level in both healthy and fistulizing tissues." (PMID 36430390, 2022). "In Crohn's disease, the expression of MMP-2 in the glandular epithelium was strong in 60% of cases while its reaction in inflammatory cells was weak in 81.8% of cases." (PMID 27034654, 2016). "For example, a comparative analysis of MMPs expression in Crohn’s disease (luminal form) and complex diverticulum disease revealed that inflamed mucosa in CD patients displayed higher expression of MMP-2, MMP-9, and MMP-13 than in diverticulitis inflamed mucosa." (PMID 36430390, 2022). "In IBD pathogenesis, MMP-2 deficits can lead to a deregulation of the intestinal barrier functions and to fibrosis; in case of increased expression, an excess of MMP-2 may induce the formation of fistulas, as seen in Crohn’s disease." (PMID 33800267, 2021). "After verifying COL1A1, CXCL10, MMP2 and FGF2 in samples from CD patients, to further verify the expression of these four genes in Crohn’s disease fibrosis, we prepared a rat model of CD fibrosis using TNBS." (PMID 37622114, 2023). "The aim of our study was to evaluate the expression of MMP-2, MMP-7, MMP-9, TIMP-1, and TIMP-2 in ulcerative colitis and Crohn's disease." (PMID 27034654, 2016). "While the top ranked genes included some P/PIs previously found to be associated with CD and/or UC, such as MMP2, MMP15 and MST1, a series of P/PI genes were identified, which have not been previously related to Crohn's disease or ulcerative colitis." (PMID 21931648, 2011).
cyst (10 papers, 2012 to 2023). A sac-like closed membranous structure that may be empty or contain fluid or amorphous material. "In our model, the specific role of MMP9 on cyst formation is suggested by the steady levels of MMP2." (PMID 38039285, 2023). "In cystic VS tissues, MMP-2 was localized to tumor cells on the cyst cavity inner surface and its levels were higher in the cystic fluid than in other samples." (PMID 34646772, 2021). "Consistent with previous studies showing that the proteolytic activity of MMPs might degrade collagen, fibronectin, laminin and contribute to cyst formation and expansion, the expression of MMP-2 and MMP-9 were upregulated in cystic VS samples compared with solid VS." (PMID 34646772, 2021). "In this study, we also compared other outcome indicators after treatment and showed that the combination was significantly better than the drugs alone, in terms of E2, P, CA-125, CA-199, MMP-2, MMP-9, Gal-3, VEGF, cyst size, and VAS." (PMID 36386543, 2022). "The prominent localization of MMP2 in this model was in the interstitium and in foci between the cysts, suggesting a role in the control of fibrosis rather than of cyst enlargement." (PMID 38039285, 2023). "Matrix metalloproteinase-2 (MMP-2) and -9 (MMP-9) may regulate collagen accumulation in CKD inflammatory sites, thus allowing cyst enlargement and limiting the severity of interstitial fibrosis." (PMID 22761655, 2012). "In addition, the combination showed significant advantages in other outcome indicators after treatment: E2, P, CA-125, CA-199, MMP-2, MMP-9, Gal-3, VEGF, cyst size, and VAS were significantly lower in patients on the combination than in those on the drugs alone." (PMID 36386543, 2022). "However, we did not observe changes in expression of MMP2 and TIMP1 protein in follicular and cyst walls." (PMID 37173342, 2023).
dementia (10 papers, 2007 to 2025). Loss of intellectual abilities interfering with an individual's social and occupational functions. "Upregulation of MMP-2 and -9 was found to be correlated with some specific tau mutants such as tau-A152T and MAPT IVS10+16 compared to control, which further highlights the roles of MMP-2 and -9 in dementia." (PMID 32466129, 2020). "There are indications that MMP-2 might play a role in the pathogenesis of AIDS-related Kaposi's sarcoma or HIV-1 associated dementia." (PMID 21364930, 2011). "Among all MMPs, MMP-2, -3, -9, and -14 were the major MMPs found in the brain, and high levels of MMP-9 and MMP-2 were observed in patients with frontotemporal dementia (second most common form of dementia)—a disorder often causing significant personality and behavior changes." (PMID 32466129, 2020). "For example, elevated levels of MMP-2, MMP-3, MMP-10, TIMP-1, and TIMP-2 were detected in the CSF of patients with delirium who had pre-existing dementia." (PMID 40507855, 2025). "Moreover, simultaneous examination of MMP-9, MMP-2, and TIMP-1 in the cerebrospinal fluid (CSF) contributed to the ability to differentiate between AD and other types of dementia." (PMID 32466129, 2020). "In contrast to SCI, previous studies using post mortem human tissue of multi-infarct induced dementia, ALS and Parkinson's disease demonstrated the expression of MMP-2 at the border of the evolving astroglial scar or in astroglia in the cerebral cortex or substantia nigra." (PMID 17594482, 2007). "Furthermore, the simultaneous investigation of MMP9, MMP2, and TIMP1 in CSF might provide the potential to distinguish between different types of dementia." (PMID 35454094, 2022). "Conversely, MMP-2, MMP-12, and TIMP-1 were higher in acute trauma (e.g., hip fracture) compared with healthy controls or patients without dementia." (PMID 40507855, 2025).
gastric adenocarcinoma (10 papers, 2012 to 2025). "The aim of this study was to investigate whether the expression of MMP2, MMP7, and MMP9 in humans is associated with the expression of mTOR in its “naïve” and its phosphorylated (active) form in different topographical regions of gastric adenocarcinomas." (PMID 26652716, 2015). "In conclusion, our results demonstrate that LPE appears to be a protective agent against the insurgence of human gastric adenocarcinoma since it can reduce the upregulation of key enzymes such as MMP-9 and MMP-2 that occur during the inflammation process." (PMID 31817563, 2019). "Astragalus saponins have also been found to inhibit human gastric adenocarcinoma cell proliferation and invasion by downregulation of the proangiogenic protein VEGF as well as the metastatic proteins metalloproteinase-2 (MMP-2) and MMP-9." (PMID 24963322, 2014). "The human gastric adenocarcinoma cell line AGS responded to IL-21 by increasing the production of MMP-2 and MMP-9 in a NF-kB-dependent fashion and treatment of H. pylori-infected gastric explants with an antibody against IL-21 decreased the production of epithelial cell-derived MMP-2 and MMP-9." (PMID 36769214, 2023).
gastric ulcer (10 papers, 2017 to 2024). An ulcerated lesion in the mucosal surface of the stomach. "The impaired healing of gastric ulcer in diabetic rats was associated with suppressed tissue expression endothelial cell markers (i.e. eNOS and peNOS), enhanced pro-inflammatory reactions (i.e. IL-1β, IL-6 and myeloperoxidase activity) and reduced regenerative activity (i.e. MMP-2, IL-10 and cAMP)." (PMID 29095895, 2017). "Regarding the healing of gastric ulcers, it can be postulated that appropriate healing will occur when activities of MMP-2 and -9 decrease gradually, given that in the late period, their actions are detrimental to the healing process." (PMID 36902320, 2023). "In the past 10 years, several animal studies with gastric ulcers have focused on the role of MMP-2 and MMP-9." (PMID 33233494, 2020). "MMP-2 became prominent in the ulcer margin from 2 to 21 days after injection of acetic acid in rats, suggesting MMP-2 is an appreciable marker in gastric ulceration and healing." (PMID 29095895, 2017). "The summation of impaired pro-angiogenesis and amplification of inflammatory responses in the gastric ulcer of diabetic rats thus led to the delayed healing process of chronic ulcer evidenced by MMP-2 expression and ulcer area." (PMID 29095895, 2017). "Thus, we demonstrated the effect of citral on temporal modulation of MMP-2 and -9 in wound healing in acetic acid-induced gastric ulcers in SD and HFD-fed mice." (PMID 36902320, 2023). "Interestingly, the results showed melatonin be able to prevent gastric ulceration by reducing the expression and secretion of pro-MMP-2 in a dose-dependent manner." (PMID 35507858, 2022). "Researchers determined that ATL III inhibited 6% ethanol-induced PRGM cell death and cell membrane damage in rat gastric mucosa, and ATL III may have an anti-gastric ulcer effect by inhibiting MMP-2 and MMP-9 in a rat model of gastric ulcer induced by 70% ethanol." (PMID 37241729, 2023). "AT-III significantly and dose-dependently suppressed gastric ulcer formation via inhibiting matrix metalloproteinase (MMP)-2 and MMP-9 expression, decreasing the extracellular matrix (ECM) damage and preventing gastric ulcer formation." (PMID 38543015, 2024). "The pharmacology network explained target genes related to the identified metabolites to possess 672 interactions between the 18 identified metabolites and 379 genes, among which PTGS2, MMP2 and PTGS1 were the top annotated genes related to gastric ulcer." (PMID 38355510, 2024). "In indomethacin-induced gastric ulcer in rats, ulcerated stomach extracts had an upregulation of 92 kDa pro-MMP9 activity and a moderate reduction in MMP2 activity." (PMID 37513300, 2023). "CUR prevented gastric ulceration and promoted the healing process by inhibiting MMP9 activity and enhancing MMP2 activity." (PMID 37513300, 2023). "Specifically, authors investigated the effect of melatonin on the regulation of MMP-2 and MMP-9 in a rat model suffering from indomethacin-induced gastric ulcer." (PMID 35507858, 2022). "The PTGS2, MMP2 and PTGS1 were the top annotated genes related to gastric ulcer." (PMID 38355510, 2024).
invasive breast carcinoma (10 papers, 2008 to 2024). A carcinoma that infiltrates the breast parenchyma. "The levels of MMP9 and MMP2 were also increased in the stroma adjacent to invasive breast carcinomas (Finak Breast)." (PMID 28423685, 2017). "MMP2 is an important collagenase which is widely expressed in invasive breast cancers." (PMID 35205651, 2022). "The over-expression of full-length Anxa2 increased the expression of three EMT-TFs such as SLUG, SIP1 and TWIST1 and two MMPs (MMP2, MMP9) in invasive breast cancer MDA-MB-231 cells." (PMID 32244350, 2020).
myocarditis (10 papers, 2013 to 2022). Myocarditis is a condition that is characterized by inflammation of the heart muscle (myocardium). "Collectively, expression and activation of MMP-2 was increased along with the DCM phenotype after myocarditis, while continued treatment with ONO-0260164 attenuated these phenomena." (PMID 34702968, 2021). "It was shown to inhibit MMP-8 in coxackie virus-induced myocarditis and MMP-2 and MMP-9 expression in experimental atherosclerosis." (PMID 34959676, 2021). "While there are no significant changes in total ventricle fibrosis, eosinophil depletion post-myocarditis leads to decreased expression of MMP2 and tissue inhibitor of metalloproteinases 2 (TIMP2)." (PMID 32322219, 2020). "In experimental models of Chagas disease, high MMP-2 and -9 proteolytic activity has been described, which suggests an important role of MMPs in T. cruzi-induced acute myocarditis." (PMID 28118356, 2017). "In line with our observations, a protective role for MMP-2 expression has been reported in experimental models of antibody-induced arthritis, autoimmune encephalomyelitis, and myocarditis." (PMID 26355684, 2015). "In this study, we found that knocking down the expression of S100A1 significantly attenuated the effects of reynoutrin on improving cardiac function, cardiomyocytes apoptosis, myocardial inflammation and fibrosis, and down-regulating the expressions of MMP2, MMP9, p-p65, and TGF-β1 in rats with IHF." (PMID 34366855, 2021). "In this context, it has been demonstrated that MMP-2 gene deletion reduces the atherosclerotic plaque lesion formation in apoE−/− mice, and is beneficial in acute myocardial infarction, while it exacerbates myocardial inflammation in viral-induced myocarditis." (PMID 26355684, 2015). "Furthermore, increased activity of cardiac MMP-2 and MMP-9 has been associated with mortality during the acute phase of T. cruzi infection, suggesting an important role in the induction of chagasic acute myocarditis." (PMID 24260222, 2013). "EP4 stimulant may be a promising and novel therapeutic agent that rescues cardiac malfunction during myocarditis and prevents adverse ventricular remodeling after myocarditis by promoting the TIMP-3/MMP-2 axis." (PMID 34702968, 2021).
nasal polyps (10 papers, 2014 to 2023). "In an experimental study using organ culture of nasal polyps, S. aureus infection promoted the release of MMP-2, MMP-9, TIMP-1, and Th2 cytokines, including IL-5, IL-13, and eotaxin." (PMID 33477617, 2021). "We have previously reported that MMP-2 expression was increased in TGF-β1-stimulated nasal polyp-derived fibroblasts." (PMID 32806646, 2020). "However, another study revealed that the increased levels of MMP-2 in nasal polyps elevated MMP-9 expression in CRSsNP, and decreased levels of TIMP-1 in both CRSsNP and CRSwNP were comparable to those in the controls." (PMID 33477617, 2021). "Two studies found an association of MMP-9 and MMP-2 polymorphisms and chronic rhinosinusitis with nasal polyps, but not in patients with recurrent nasal polyps." (PMID 28400178, 2017). "Previous studies provided evidence for higher levels of MMP‐1, MMP‐2, MMP‐3, MMP‐7, MMP‐8, and MMP‐9 in nasal polyps." (PMID 34504680, 2021). "The elevated expression of MMP-2, -7 and -9, important endopeptidases for degrading the ECM, has been considered to play important roles in the pathogenesis of nasal polyposis in CRS patients." (PMID 33326455, 2020). "Previous studies demonstrated that TGF-β1, MMP2, MMP7, and MMP9 could induce EMT in nasal polyps and can be synthesized and secreted by macrophages." (PMID 35990621, 2022). "Other studies found an association of nasal polyps with MMP-9 polymorphisms, but not with MMP-2 ones." (PMID 28400178, 2017). "Furthermore, vitamin D derivatives could significantly inhibit TNF-α-induced matrix metalloproteinase-2 (MMP-2) and matrix metalloproteinase-9 (MMP-9) secretion in fibroblasts involved in nasal polyp genesis." (PMID 34440059, 2021). "However, expressions of MMP-2 and MMP-9 are not sensitive to LPS exposure in nasal polyp fibroblasts." (PMID 25390332, 2014).
psoriasis (10 papers, 2013 to 2024). An autoimmune condition characterized by red, well-delineated plaques with silvery scales that are usually on the extensor surfaces and scalp. "Even after adjusting for sex and age, psoriasis resulted to be strongly associated with lower MMP-2 levels." (PMID 36293148, 2022). "The high concentration of MMP2 during psoriasis eruption and its significant reduction after successful treatment and eliminating symptoms of the disease indicate that this enzyme may be associated with psoriasis." (PMID 34715781, 2021). "MMP2 is increased in psoriasis and MMP9 is increased in atopic dermatitis, psoriasis, and urticaria." (PMID 34299145, 2021). "The activation of MMP2 promotes remodeling of the extracellular matrix in inflammatory processes, characteristic of the psoriasis condition." (PMID 34715781, 2021). "TIMP2 may be a key molecule in the activation of MMP2 in psoriasis and, in this manner, contribute to the inflammatory process." (PMID 34715781, 2021). "Significant decrease of MMP-9 and MMP-2 levels in the sera was associated with clinical improvement and with the decrease of TNF-α, VEGF, and E-selectin, angiogenic molecules already known to be implicated in clinical expression of psoriasis." (PMID 24396598, 2013). "Keratinocytes can also produce a variety of matrix metalloproteinases (MMPs), such as MMP2, MMP3, and MMP9, which are involved in the inflammatory responses, cell migration, and angiogenesis in psoriasis." (PMID 36555642, 2022). "We found that MMP2, MMP12, MMP13, TIMP2, and TIMP4 distinguished psoriasis from psoriatic arthritis patients undergoing a systemic treatment, with a good diagnostic accuracy (Area under the ROC Curve (AUC) > 0.7)." (PMID 31717649, 2019). "Fleischmajer and collaborators showed an increase in the expression of MMP2 and TIMP2 in the skin of psoriasis patients, while other researchers showed an increase in the plasma levels of MMP2 and TIMP2 in psoriasis patients compared to the level observed in the plasma of healthy individuals." (PMID 34715781, 2021). "A set of biomarkers, composed matrix metalloproteinases, and their tissue inhibitors comprises MMP2, MMP12, MMP13, TIMP2, and TIMP4 whose circulating levels are higher psoriasis undergoing systemic therapy compared to the parallel with psoriatic arthritis cohort." (PMID 34715781, 2021). "Additionally, similar to psoriasis and RA synovial fibroblasts, higher levels of EPCR were also found on RA circulating T cells, and blocking this receptor can stimulate Th2 and Treg cells and anti-inflammatory MMP-2 production in RA PBMCs." (PMID 37228024, 2024). "The localization of MMP2 in the skin is preferentially in the epidermis, specifically the lowest layer (basal membrane); however, in the skin samples from the Control (blepharoplasty) and the non-affected skin of patients with psoriasis, the immunolabeling is more dispersed throughout the epidermis." (PMID 34715781, 2021).
pulmonary hypertension (10 papers, 2006 to 2024). Increased pressure within the pulmonary circulation due to lung or heart disorder. "A recent study has shown that legumain increases the synthesis of ECM proteins by activating MMP-2/transforming growth factor-β1 signaling in pulmonary artery VSMCs in a mouse model of pulmonary hypertension." (PMID 31060209, 2019). "In addition, l-arginine also attenuated APE-induced pulmonary hypertension through other mechanisms, including the modulation of NO synthesis and downregulation of MMP-2 and MMP-9 activities." (PMID 34737702, 2021). "The correlation between MMP-2 expression and progression of pulmonary hypertension in the described animal model indicated important roles of this proteinase in different vascular remodeling processes that involves smooth muscle cell proliferation, migration and intimal thickening." (PMID 27894297, 2016). "In our study, SSE decreased expression of MMP2 and MMP9 in the carotid artery in the balloon injury model, as well as the lung in the pulmonary arterial hypertension model." (PMID 33790787, 2021). "The MMP2/TIMP4 ratio was detected as a marker of myocardial dysfunction and as a negative predictor for survival in idiopathic pulmonary hypertension." (PMID 36293543, 2022).